BRCA2 (BRCA2 DNA repair associated)
Diseases named in the same sentence as BRCA2 in open-access papers (continued):
Sharing a sentence is not in itself a finding about the gene and the disease.
gastric cancer (continued). "Our results confirm that BRCA2 gene mutations are also associated with familial aggregations of not only breast but also of stomach cancer." (PMID 12373604, 2002). "Currently there is little information about the nature and frequency of BRCA2 constitutional mutations in families selected for the coexistence of breast and stomach cancers." (PMID 12373604, 2002). "In three families the association of detected abnormalities in the BRCA2 gene with stomach cancer was supported by analyses of the occurrence of these changes in relatives." (PMID 12373604, 2002). "In the TCGA WES gastric cancer cohort, three BRCA2 deficient, four PALB2 deficient, two BRCA1 deficient and three BRCA1 promoter methylated cases all had an HRD score ≥42 (p < 1 × 10-5, Fisher exact test), which is the threshold for HR deficiency previously defined for ovarian cancer." (PMID 38589664, 2024). "Recently, an association between BRCA2 and gastric cancer has been reported." (PMID 35912179, 2022). "In family 32, p.M1I in CDH1 and p.T1354M in BRCA2 are implicated in gastric cancer and BC respectively and knowing that the family presented with only BC, two hypothesis can be formulated." (PMID 28202063, 2017). "It has been suggested that the frequency of stomach cancer appears greater among Polish families with BRCA2 mutations but again this could be due to a higher proportion of participants of Jewish decent." (PMID 26236408, 2015). "The SIRs for breast and stomach cancer in the families presented in this report is highly significant, indicating that it is a real entity and not a chance association, and it provides additional evidence that male stomach cancer is part of the spectrum of disease in BRCA2 families." (PMID 12373604, 2002). "Recent evidence suggests that carriers of a pathogenic germline variant (PGV) in BRCA1 or BRCA2 may have an increased risk of gastric cancer (GC)." (PMID 42286806, 2026). "With regard to gastric cancer, most cases in our cohort were observed in families carrying PVs in BRCA2 and CDH1." (PMID 40649708, 2025). "The results highlight that epigenetic mechanisms, particularly methylation of RAD51, BRCA1, and BRCA2 genes, are frequently involved in gastric cancer development and progression." (PMID 40869030, 2025). "In the TCGA gastric cancer WES dataset, we identified two cases with a pathogenic BRCA2 mutation accompanied by LOH, one BRCA2 case where both alleles had pathogenic mutations, and two cases with pathogenic BRCA1 mutation accompanied by LOH." (PMID 38589664, 2024). "Among 40 females with BC and gastric cancer, 10 had PVs: BRCA2 (n = 3, 7.5%, 95% CI 2.0–21.5%) was the most frequent, followed by PALB2 (n = 2, 5.0%, 95% CI 0.9–18.2%) and CHEK2 (n = 2, 5.0%, 95% CI 0.9–18.2%)." (PMID 36856935, 2023). "In this case-control study of 63 828 patients with 14 common cancer types and 37 086 controls, pathogenic variants in BRCA1 were associated with biliary tract cancer, in BRCA2 with esophageal cancer, and in BRCA1/2 with gastric cancer." (PMID 35420638, 2022). "We observed that biliary tract, esophageal, and gastric cancer were significantly associated with BRCA1 and/or BRCA2 pathogenic variant status in addition to the 4 established cancer types." (PMID 35420638, 2022). "Among the BRCA2-mutated families, the most frequent tumours were prostate, lung, CRC and gastric cancer (24.3, 15.7, 14.3 and 8.6%, respectively)." (PMID 29884136, 2018).
gastric cancer (continued). "Further research, including sequencing of entire sequences of BRCA1 and BRCA2 genes, is necessary to ultimately determine their role of these two genes in gastric cancer in Poland." (PMID 26779294, 2016). "Our results confirm and extend the notion that BRCA2 is likely to be the molecular basis of at least a subset of stomach cancer patients." (PMID 12373604, 2002). "In families where the occurrence of breast and stomach cancers was among 1° relatives, BRCA2 abnormalities were detected in two out of 12 cases (one frameshift, one assumed missense variation; 16.7%)." (PMID 12373604, 2002). "Verification of this relationship between breast and stomach cancer in our series of cases suggests that this disease constellation can be used as a phenotypic indicator for the pre-selection of families for BRCA2 testing." (PMID 12373604, 2002). "In families with stomach cancers among 2° relatives, BRCA2 changes were identified in four out of 17 cases (two frameshifts, two assumed missense variations; 23.5%)." (PMID 12373604, 2002). "However, the relationship between BRCA2 mutations and gastric cancer (GC) remains understudied." (PMID 41769559, 2026). "The identification of mutations in BRCA2, PIK3CA, and fibroblast growth factor receptor 2 (FGFR2) genes particularly underscored their potential as predictive biomarkers and therapeutic targets in gastric cancer." (PMID 40869030, 2025). "Additionally, 4 patients attained SD ≥ 24 weeks including two patients with ampullary and gastric cancers, carrying germline BRCA2_c.8633-1 G > C and BRCA2_Trp2628Ter, respectively, who exhibited sustained response over a year." (PMID 39085400, 2024). "However, in gastric cancer, mutation rates in HRD genes (BRCA1 and BRCA2) are low, and individual PARP inhibitors have limited efficacy." (PMID 35480096, 2022). "BRCA2 mutation increased gastric cancer incidence (RR 2.15 [1.98–2.33]), whereas BRCA1 did not increase gastric cancer incidence." (PMID 34577828, 2021). "We found that almost 24 % of cases whose family members had stomach cancer carried a BRCA2 mutation vs. 4 % without stomach cancer in the family history." (PMID 26779294, 2016). "Test results indicate a mutation in a gene responsible for stomach cancer (but no BRCA1 or BRCA2 mutation)." (PMID 27586379, 2016). "It has previously been suggested that the increased frequency of stomach cancers in BRCA2 carriers may be sex related as it has been reported to occur primarily in males." (PMID 26236408, 2015). "The second in frequency BRCA2 frameshift mutation c.5851_5854delAGTT, located in exon 11, was found in two patients (1 %): BC76 with a family history of BC and stomach cancer, diagnosed with TNBC at the age of 53, and BC58 with family history of BC and CRC, diagnosed with BC at the age of 48." (PMID 26183948, 2015). "There is also evidence to suggest that the increased frequency of stomach cancers in BRCA2 carriers may be sex related, as it occurs primarily in males." (PMID 12373604, 2002). "Although the LOH of BRCA2 was absent in the gastric cancer sample, somatic mutation of BRCA2 may contribute as a second-hit event of BRCA2." (PMID 35912179, 2022). "The majority of published analyses on the correlation between BRCA1 and BRCA2 mutations and GC are indirect and based on the observation of GC incidence in families with detected mutation, but do not show the prevalence of BRCA1/2 mutations in patients with diagnosed gastric cancer." (PMID 26779294, 2016). "Indeed, we have also observed that knock-down of BRCA1 or BRCA2 could sensitize Olaparib effect in MKN28 gastric cancer cells." (PMID 26540566, 2015).
gastric cancer (continued). "Since cancers with defective homology directed double-strand break repair due to BRCA1 or BRCA2 mutations are particularly sensitive to platinum therapy and PARP inhibitors, it is conceivable that this subset of gastric cancers might also benefit from their usage." (PMID 26511885, 2015). "Also, multiple other studies have shown that BRCA2 mutation but not BRCA1 is correlated with gastric cancer." (PMID 25349615, 2014). "Importantly, there has been a steady accumulation of clinical data suggesting that BRCA2, and to a slightly lesser extent BRCA1, carriers also have an increased risk of gastric cancer (GC)." (PMID 41256354, 2025). "In this review, we discuss emerging evidence that BRCA2 PV carriers, and likely also BRCA1 PV carriers, are also at increased risk for gastric cancer (GC), highlighting that GC may be part of the BRCA1/2 cancer risk spectrum." (PMID 36497436, 2022). "Different gastric cancer cell lines were examined regarding their protein levels of BRCA1, BRCA2 and c‐MET using Western blot analysis." (PMID 32686903, 2020). "Further investigations are needed in order to describe the actual involvement of BRCA2 mutations in different types of familial aggregation of cancers and to assess whether or not there are histopathological differences in stomach cancers that are associated with mutations in this gene." (PMID 12373604, 2002). "The results showed that RAD51D was not a risk factor for gastric cancer, but other BRCA1, BRCA2, and ATM genes from the homologous recombination pathway are risk factors for gastric cancer." (PMID 39206620, 2024). "Markers useful for therapeutic decision not included in this panel are BRCA1 and BRCA2, important predictive indicators for breast, ovarian, and gastric cancers." (PMID 32340363, 2020). "Both, BRCA1 and BRCA2 variants were associated with higher HRD scores in BRCA (FDR < 1.3 × 10−42) and OV (FDR < 5.0 × 10−12), BRCA2 (but not BRCA1) variants were also associated with higher HRD of PAAD (FDR = 1.3 × 10−17) and stomach cancer (STAD) (FDR = 6.7 × 10−17)." (PMID 34572800, 2021). "Analysis of the selected literature suggests that mutation of the BRCA2 gene, rather than BRCA1 gene, has a greater influence on the risk of developing prostate, pancreas and stomach cancers, as well as impacting on the survival and age of onset of these cancers." (PMID 26236408, 2015). "Thus, gastric cancers with signature 3 mutations bear other mutational hallmarks of failure of homology directed double-strand break repair, despite the absence of inactivating mutations in BRCA1 and BRCA2 genes." (PMID 26511885, 2015).
Hereditary breast cancer (51 papers, 2001 to 2024). Breast carcinoma that has developed in relatives of patients with history of breast carcinoma. "Germline variants in BRCA1 and BRCA2 (BRCA1/2) genes are the most common cause of hereditary breast cancer." (PMID 37656691, 2023). "Hereditary breast and ovarian cancer (HBOC) associated with BRCA1 and BRCA2 mutations is the most common form of hereditary breast cancer." (PMID 35742117, 2022). "Germ-line mutations in BRCA2 act as a major cause of hereditary breast cancer and increase the risk of its early-onset." (PMID 33662042, 2021). "The other three polymorphisms (rs11571707, rs11571769, rs144848) of the BRCA2 gene evaluated here are related to hereditary breast cancer." (PMID 33499154, 2021). "People carrying pathogenic variants of the BRCA1 and BRCA2 genes are often referred to as those having predisposition for ‘hereditary breast cancer’." (PMID 28939999, 2018). "BRCA1 and BRCA2 are tumor suppressor genes and these mutations were strongly associated with hereditary breast cancer." (PMID 25774336, 2015). "Mutations in the BRCA1 and BRCA2 genes are responsible for only a part of hereditary breast cancer (HBC)." (PMID 22114986, 2011). "The BRCA1 and BRCA2 germ-line mutation is known associated with the hereditary breast cancer; and the MMR germ-line mutation (especially hMLH1) for the hereditary nonpolyposis colorectal carcinoma (HNPCC)." (PMID 18973653, 2008). "DNA sequencing performed by Myriad Genetic Laboratories on patient III: 22, who had lobular breast cancer, uncovered a BRCA2 exon 3 542G>T mutation, predicted to result in a truncated protein (L105X)." (PMID 14735197, 2004). "When pathogenic/likely pathogenic mutations were aggregated within each gene, the association was confirmed for three genes in the UKB at p < 0.0056 (Bonferroni correction for nine tests), including CHEK2, ATM and BRCA2, all also known to be associated with hereditary breast cancer." (PMID 36816149, 2023). "BRCA1 and BRCA2 genes were identified as causative genes for early-onset hereditary breast cancer." (PMID 33593852, 2021). "BRCA1 and BRCA2 are among the genes associated with hereditary breast cancer." (PMID 26770289, 2016). "Two loci were associated with lobular breast cancer for BRCA2 carriers: 11q23.3 and Xp11.23." (PMID 25919761, 2014). "There were 2 (BRCA2) mutations in the patients with hereditary breast cancer." (PMID 23519070, 2012). "However, mutations in the two major genes, BRCA1 and BRCA2, are found in only 15% to 20% of hereditary breast cancer (HBC) families." (PMID 22114986, 2011). "The familial association of lobular breast cancer could mainly be due to patients with BRCA2 mutation or the occurrence of hereditary diffuse gastric cancer." (PMID 22117567, 2011). "In the present study, we showed that BRCA2 MBCs are more likely than BRCA2 FBCs to be ER+ and PR+, thus suggesting that susceptibility to hereditary breast cancer may be influenced by differences in hormonal background between male and female BRCA2 mutation carriers." (PMID 26857456, 2016). "Germline variants in two high penetrance genes, BRCA1 and BRCA2 (BRCA1/2), are the most common cause of hereditary breast cancer." (PMID 37656691, 2023). "On the other hand, our finding of stronger statistical evidence for genes known to be associated with hereditary breast cancer (CHEK2, ATM and BRCA2) is novel." (PMID 36816149, 2023). "Hereditary breast cancer accounts for 10% of new cases and 4%–5% of cases are associated to pathogenic variants in BRCA1 or BRCA2 genes." (PMID 38414963, 2023). "There are also associations of CPT-1A with the wild-type variants of moderate to highly penetrant genes e.g. BRCA1, BRCA2 and ATM involved in hereditary breast cancer." (PMID 36180554, 2022). "The interaction between PALB2 and BRCA2 is important for maintaining genomic integrity.Moreover, BRCA2 and BRCA1 are the most common causes of hereditary breast cancer." (PMID 34092963, 2021).
Hereditary breast cancer (continued). "This review will focus on the surgical and systemic treatment of hereditary breast cancer with a particular focus on BRCA1 and BRCA2 mutations." (PMID 33194613, 2020). "Hereditary breast cancer with germline mutations in BRCA1 and BRCA2 genes are characterized by a deficiency in DNA repair mechanisms that renders these tumors sensitive to platinum agents." (PMID 30038706, 2018). "The BRCA2 gene, when altered, is responsible for approximately 30 to 40 % of all cases of hereditary breast cancer." (PMID 26770289, 2016). "Specific pathological features have been reported in hereditary breast cancer with differences between BRCA1 and BRCA2 associated tumors." (PMID 19619314, 2009). "Hereditary breast cancers linked to germ-line mutations of BRCA1 and BRCA2 genes almost invariably show allelic imbalance (AI) at the respective loci." (PMID 11710835, 2001). "This is in contrast to other types of cancer like hereditary breast cancer, for which BRCA1 and BRCA2 account for more than half of the PVs identified in patients with this diagnosis." (PMID 34255164, 2021). "South Americans in general, and specifically Peruvian hereditary breast cancer populations, are not well characterized with mutations in BRCA1 and BRCA2 genes, and a founder effect has not been identified." (PMID 28944232, 2017).